INS (insulin)
Diseases named in the same sentence as INS in open-access papers (continued):
Sharing a sentence is not in itself a finding about the gene and the disease.
Hyperglycemia (continued). "In the D1 condition, the response of the system is similar to what is observed in type 1 diabetics who are unable to synthesize insulin in response to hyperglycaemia." (PMID 22509346, 2012). "RSV has also been shown to reverse hyperglycemia and improve insulin sensitivity in high-fat-induced obese rodents and in a type 1 diabetic animal model." (PMID 23226280, 2012). "On the other hand, the higher dose of glibenclamide (2.5 mg/kg), one of the sulfonylureas that stimulates insulin secretion, and metformin, one of the iguanids that inhibits hepatic glucose output, improved hyperglycemia after oral glucose load." (PMID 22474494, 2012). "Both young and old GK showed marked hyperglycemia with normal insulin level and well-preserved endothelium-dependent and endothelium-independent vasodilation in aorta and carotid artery." (PMID 21977022, 2012). "Longitudinal studies of subjects who eventually develop T2DM reveal a progressive rise in serum insulin levels in the prediabetic phase that is followed by a decline in serum insulin levels upon development of fasting hyperglycemia." (PMID 22110477, 2012). "Typically, the DIO model is characterized by increased body weight gain, hyperglycemia, and establishment of insulin-resistant state (hyperinsulinemia, increase of the leptin/adiponectin ratio, ectopic fat storage in the liver and muscle)." (PMID 22888363, 2012). "In β-cell lines or isolated rat islets, incubation with antioxidant N-acetyl cysteine or overexpression of antioxidant enzyme glutathione peroxidase prevented the deleterious effects of hyperglycemia on insulin gene expression." (PMID 23226280, 2012). "At later stages, β-cell function is affected leading to a decrease in insulin release and lower levels of plasma insulin, which favors hyperglycemia." (PMID 22470480, 2012). "Desensitization to insulin in the presence of hyperglycaemia in-vitro has been widely documented for many cell types and has also been shown in co-cultures of adipocytes and hepatocytes." (PMID 22509346, 2012). "Hyperglycemia developed in the first 24 hours of life, and insulin therapy was required for 6 weeks before resolution occurred." (PMID 22781086, 2012). "Endogenous insulin secretion is predictive of postprandial hyperglycaemia and response to prandial exogenous insulin." (PMID 22681724, 2012). "Type I diabetes mellitus (T1DM), is an insulin dependent condition which results in hyperglycemia due to the destruction of pancreatic β cells that synthesize and secrete the hypoglycemic protein, an essential hormone for carbohydrate metabolism." (PMID 23675270, 2012). "The clinical benefits of intensive insulin therapy for prevention of hyperglycaemia after surgery are yet controversial." (PMID 22870170, 2012). "We found that the elevated levels of CTGF mRNA and protein induced by hyperglycemia were prevented by exogenous insulin treatment." (PMID 22511849, 2012). "Correction of hyperglycemia by insulin or phlorizin restored the gene expression of cardiac KATP in these diabetic rats." (PMID 22257425, 2012). "It is clinically characterized by hyperglycemia due to the destruction of insulin-producing β-cells by diabetogenic T cells." (PMID 22807927, 2012). "Hyperglucagonemia and abnormal insulin-to-glucagon ratios observed in subjects with T2D contribute to pathologic hyperglycemia in both postabsorptive and fasting states by increasing hepatic glucose production." (PMID 23226550, 2012). "When the ob/ob mutation is placed on a BTBR background, the mice are initially insulin resistant with elevated insulin levels, pancreatic islet hypertrophy, and marked hyperglycemia by 6 weeks of age." (PMID 22461787, 2012). "Subsequently it was challenged with insulin and high glucose concentrations to simulate hyperglycaemia." (PMID 22509346, 2012). "Here, we present the results of a number of studies where protocol-directed insulin infusions improve perioperative hyperglycaemia in critical care." (PMID 24764523, 2012).
Hyperglycemia (continued). "Mouse CD4 T-cells specific for a low-affinity insulin-derived peptide required 20 weeks before hyperglycemia developed in 50% of recipient mice." (PMID 23155466, 2012). "Our findings indicate that when lowering blood glucose, insulin administration abrogates the adaptive mechanisms of long-term severe hyperglycemia and promotes intima hyperplasia at the same time." (PMID 21977022, 2012). "These deficits and the corresponding neurophysiological structural and functional alterations are linked to both metabolic and vascular changes, related to chronic hyperglycaemia, but probably also defects in insulin action in the brain." (PMID 22383997, 2012). "Second, since both of these studies used oral glucose tolerance testing to induce hyperglycemia, insulin levels increased at the same time as plasma glucose levels." (PMID 22701470, 2012). "One of the diabetic patients who developed hyperglycemia was treated with insulin and the other with additional oral hypoglycemic agents." (PMID 22523651, 2012). "As a result of the thus induced fetal hyperglycemia, the fetal pancreas, although immature, is capable of producing increased levels of insulin, which in turn acts as a growth hormone and promotes growth and adiposity in the fetus." (PMID 23227034, 2012). "DM is part of a group of metabolic diseases that is characterized by hyperglycemia originating from defects of insulin secretion by the pancreatic β-cells and/or insulin action in the peripheral tissues." (PMID 23202902, 2012). "Insulin injection corrected hyperglycemia in GK but induced endothelium dysfunction and intima hyperplasia." (PMID 21977022, 2012). "By reducing hyperglycemia via a non–insulin-dependent mechanism, SGLT2 inhibition decreases the demand on beta cells to secrete insulin." (PMID 22355316, 2012). "A model of ALI (LPS at a dose of 5.0 mg/kg) with non-hyperglycemia was established in Sprague-Dawley rats receiving continuous exogenous insulin by micro-osmotic pumps and wortmannin." (PMID 22458687, 2012). "DM is a group of metabolic diseases characterized by hyperglycemia due to defects in insulin secretion by pancreatic β-cells, insulin action on target tissues, or both." (PMID 22919462, 2012). "Pharmacotherapy with insulin is a potential means of managing hyperglycaemia in this group of patients especially since a significant proportion are insulinopaenic." (PMID 22894705, 2012). "In this context, it has been shown that deletion of ghrelin gene promotes insulin release and ameliorates glucose intolerance and hyperglycemia in a diabetic and obese mice model." (PMID 23162532, 2012). "Insulin reverses the harmful effects of hyperglycemia on vascular oxidative stress by increasing myocardial glucose uptake, diminishing the inflammatory response, and decreasing apoptosis." (PMID 23209941, 2012). "Controlling hyperglycemia in diabetic patients with insulin or other hypoglycemic agents and the reduction of oxidative stress, ROS production and inflammation result in the attenuation of diabetic complications especially DN." (PMID 22991571, 2012). "Effectiveness of Tecomella undulata in acute hyperglycemia can be explained by insulin secreting properties of its alkaloid and terpenes contents." (PMID 22769229, 2012). "We have shown that patients with less endogenous insulin secretion have greater post meal hyperglycaemia and greater response to prandial exogenous insulin." (PMID 22681724, 2012). "The benefit of insulin infusion in patients with hyperglycemia in ACS has yet to be demonstrated convincingly in a large prospective clinical trial." (PMID 22830071, 2012). "The expression patterns of miR-27a varied with hyperglycemia in the Gyoto-Kakizaki rat, and miRNA-143 overexpression inhibited insulin-stimulated AKT activation and resulted in impaired glucose metabolism." (PMID 22655170, 2012). "A reduction in endogenous insulin production results in an increase in plasma glucose (hyperglycemia)." (PMID 22973412, 2012).
Hyperglycemia (continued). "In the Hyperglycemia: Intensive Insulin Infusion in Infarction (HI-5) study, patients with ACS presenting with glucose levels >140 mg/dL had a significantly higher six-month mortality rate." (PMID 23209941, 2012). "Hyperglycemia was controlled by applying an intensive insulin protocol with a target glycemia of 150 mg/dL." (PMID 25161774, 2012). "In the diabetic state, hyperglycemia per se and subsequent induction of oxidative stress decrease insulin gene expression and secretion and finally bring about apoptotic cell death." (PMID 23202973, 2012). "Insulin is known to stimulate mouse preimplantation embryo biosynthesis, proliferation, endocytosis and subsequent fetal growth while hyperglycaemia and maternal diabetes compromise early development." (PMID 23300778, 2012). "Iron-deficient animals also display signs of disrupted metabolic homeostasis, including alterations in insulin signaling, as evidenced by hyperglycemia, hyperinsulinemia, and hyperlipidemia." (PMID 23110872, 2012). "This mild hyperglycemia results in an enhancement of the β‐cell cycle leading to more β‐cells which in turn can produce further insulin." (PMID 23164557, 2012). "In our studies, chronic constant maternal hyperglycemia (CHG group) for one week increased basal fetal insulin concentrations." (PMID 23133755, 2012). "In contrast to the acute vasodilatory effect of hyperglycemia during constant insulin infusion, we also saw vasodilation with correction of hyperglycemia from baseline to euglycemia during both studies." (PMID 22701470, 2012). "In cases of impaired consciousness or vomiting, glucose should be infused (plus IV insulin at a starting dose of 0.05 units/kg/h in case of hyperglycemia) as soon as possible to maximise energy intake." (PMID 22642880, 2012). "Such an ectopic expression of these genes in BM-MSCs possibly can be attributed to body’s adaptive mechanism in the management of hyperglycemia, since HI (increased insulin levels in circulation) precedes onset of IR and T2D." (PMID 23144726, 2012). "It is clear that a reduction in endogenous insulin production precipitates the onset of hyperglycemia." (PMID 22973412, 2012). "Frequent postoperative hyperglycaemia in cardiac surgery patients has led to the initiation of an insulin infusion sliding scale for quality improvement." (PMID 24764523, 2012). "In many obese subjects, and more particularly so in subjects with abdominal obesity, these effects of insulin are blunted, resulting in post-prandial hyperglycemia and hyperlipemia in spite of a normal or even increased insulin secretion." (PMID 22613805, 2012). "Since previous studies reported a hypoglycemic effect in insulin resistant HF-fed and db/db mice, we first investigated the effects of OA on hyperglycemia in a T2D model generated by chronic HF feeding in combination with low doses of STZ." (PMID 22860063, 2012). "This is expected, because patients with more sever hyperglycemia are more likely to have been prescribed oral agent and/or insulin compared with patients with milder hyperglycemia." (PMID 23119180, 2012). "Although persisting hyperglycaemia necessitated euthanasia of the mice, injection of insulin-secreting cells into the vascularised chambers was tractable and their survival an indication of their potential to reverse less severe hyperglycaemia." (PMID 23152835, 2012). "In a meal test in 40 diabetic patients, 10 mg mitiglinide administration stimulated rapid insulin secretion, accompanied by reduction of postprandial hyperglycemia." (PMID 22748110, 2012). "There were “non responders” among the volunteers with T1DM where the application of SNP had little effect either on the hyperglycemia or on the plasma insulin level." (PMID 23675270, 2012).
Hyperglycemia (continued). "In an attempt to know the role of hyperglycemia and/or hypoinsulinemia in the changes of cardiac KATP channels in insulin-deficient diabetic rats, exogenous insulin was administrated for 4 days into the diabetic rats, 8 weeks following induction with STZ." (PMID 22257425, 2012). "Our results show that in addition to increased insulin resistance in peripheral tissues, augmented endogenous glucose production is also important to generate the higher hyperglycemia in 6-month-old obB1B2KO mice." (PMID 22829877, 2012). "Insulin reduced hyperglycemia by facilitating glucose disposal from blood circulation into insulin-responsive cells such as muscle, adipose, and liver." (PMID 22701507, 2012). "Once hyperglycemia becomes apparent, β-cell function such as insulin biosynthesis and secretion progressively deteriorates." (PMID 23202973, 2012). "Attenuation of both GLP-1 and insulin-induced glucose metabolism by hyperglycemia is likely to occur downstream of PI3K." (PMID 22937169, 2012). "More prolonged constant fetal hyperglycemia ultimately results in a decline in basal fetal insulin concentrations to even lower values than those seen in normal fetuses." (PMID 23133755, 2012). "A small number of prospective trials have used insulin infusions to treat hyperglycemia and/or promote growth." (PMID 22871230, 2012). "Neutrophil phagocytic activity was better preserved in patients on a continuous insulin drip than those who received only an intermittent insulin bolus to treat perioperative hyperglycemia." (PMID 23209941, 2012). "Acute intragastric administration of Olanzapine clearly mimicked the adverse metabolic side-effects known from patients, as it induced both hyperglycemia and insulin resistance, both at hepatic and extra-hepatic levels." (PMID 22905238, 2012). "An alternative protocol to test efficacy in an insulin-dependent state is to introduce plant therapy to spontaneously or experimentally induced models which have already developed severe hyperglycemia and are controlled by exogenous insulin injections." (PMID 22899950, 2012). ">A pathogenic role for tumor necrosis factor-alpha (TNF-α) in mice with Type 1- and 2- diabetes and the efficacy of anti- TNF-α treatment in ameliorating hyperglycemia and restoring normal insulin has been recently addressed." (PMID 22867128, 2012). "It is well established that insulin administration should increase plasma glucose clearance thus limiting damaging effects of acute and chronic hyperglycemia (‘glucotoxicity’)." (PMID 23091615, 2012). "STZ-induced diabetic rats had body weight maintained and hyperglycemia moderated by daily insulin injections for 6 weeks." (PMID 23285265, 2012). "But, long-term hyperglycemia stimulated to induce the production of amylin that can inhibit insulin releasing, also inhibit insulin-stimulated glucose transport in skeletal muscle and the glucose metabolism of liver cell." (PMID 23209930, 2012). "Glucagon, secreted by alpha-cells, is antagonistic to insulin and stimulates glucose release which potentially contributed to the hyperglycemia in HFP males." (PMID 22988521, 2012). "In the present study, currently recommended glucose intakes (iatrogenically) aggravated hyperglycemia, making patients eligible for insulin therapy on the basis of this threshold." (PMID 23031354, 2012). "Stimulation of insulin secretion from pancreatic β cells is one of the mechanisms by which antidiabetic agents reduce hyperglycemia." (PMID 22701507, 2012). "The secreted insulin then facilitates glucose uptake in insulin-sensitive cells such as muscle, liver, and adipocytes, hence reduces hyperglycemia." (PMID 22701507, 2012). "Postprandial hyperglycemia stimulates insulin secretion, which acts on the liver to suppress glucose production." (PMID 23316165, 2012).
Hyperglycemia (continued). "Autoreactive CD4 and CD8 T-cells in NOD mice infiltrate and subsequently destroy the insulin-producing beta-cells in pancreatic islets, resulting in dysregulation of blood glucose levels and hyperglycemia." (PMID 23155466, 2012). "Insulin is also recommended, even for limited periods of time, in patients with severe hyperglycemia, when a rapid reduction of glucose toxicity can be of great help in restoring beta cell function." (PMID 23209929, 2012). "Recognition of these autoantigens, primarily insulin peptide, by diabetogenic T cells initiates the autoimmune response that leads to the ultimate destruction of insulin-producing β-cells and hyperglycemia." (PMID 22807927, 2012). "While TZDs are effective in lowering hyperglycemia, largely by an insulin sensitizing action, concerns over the adverse effects of TZDs on an increased risk of heart failure and bladder cancer have restricted their long-term use." (PMID 22860063, 2012). "On the other hand, the db/db mouse rapidly develops hyperglycemia since their pancreatic β-cells are unable to maintain the high levels of insulin secretion required throughout life." (PMID 22899950, 2012). "Diabetes mellitus is a group of metabolic diseases characterized by hyperglycemia as a result of the impairment of insulin secretion, its action, or both." (PMID 23326021, 2012). "This hyperglycemia was reversed by insulin replacement in a dose-dependent manner resulting in progressively elevated insulin levels." (PMID 22745692, 2012). "Women with more severe hyperglycaemia and those who are unable to achieve glycaemic goals with diet and exercise require insulin to control their GDM." (PMID 22988897, 2012). "Hyperglycemia in children after cardiac surgery can be treated with intensive insulin therapy, but hypoglycemia is a potential serious side effect." (PMID 23031354, 2012). "Various authors have shown in various in vivo studies that insulin alone can stimulate beta-cell mass, whereas other authors have found that it promotes growth only in the presence of hyperglycaemia." (PMID 22577380, 2012). "Rodent studies show that resveratrol decreases blood glucose, blood insulin, and glycated hemoglobin, as well as increases insulin sensitivity in animals with hyperglycemia." (PMID 22479202, 2012). "Compared with HF feeding alone, T2D mice displayed hyperglycemia (>2 fold, p<0.01), hypertriglyceridemia (50%, p<0.05) and reduced plasma insulin level (50%, p<0.01) while retaining a similar level of liver steatosis." (PMID 22860063, 2012). "This study showed that both sEH knockout and t-AUCB treatment prevented hyperglycaemia in type I diabetes through enhanced islet glucose-stimulated insulin release by the alternate pathway and decreased islet cell apoptosis." (PMID 22007192, 2012). "Critically ill patients often present increased insulin resistance and stress-induced hyperglycemia." (PMID 22917085, 2012). "ObB1B2KO mice can compensate the absence of kinin receptors through higher capacity to secrete insulin at 3 months of age, but show higher hyperglycemia at 6 months of age." (PMID 22829877, 2012). "We investigated large vessel function in lean Goto-Kakizaki diabetic rats (GK) and Otsuka Long-Evans Tokushima Fatty diabetic rats (OLETF) with possible roles of hyperglycemia/hyperosmolarity and insulin." (PMID 21977022, 2012). "Frequent postoperative hyperglycaemia in cardiac surgery patients has led to the instigation of a quality improvement insulin infusion sliding scale." (PMID 24764523, 2012). "Another study by Ceriello and colleagues also demonstrated the beneficial effects of targeting hyperglycemia and oxidative stress simultaneously using insulin and antioxidant (vitamin C), respectively on oxidative stress and endothelial dysfunction." (PMID 22489136, 2012). "It is, thus, important to assure that appropriate rapid acting insulin is given before each meal to decrease hyperglycemia induced vascular dysfunction." (PMID 22701470, 2012).